TTN (titin)
Diseases named in the same sentence as TTN in open-access papers (continued):
Sharing a sentence is not in itself a finding about the gene and the disease.
tumor (162 papers, 2014 to 2026). "We first defined “Titin (TTN) inactivation”, a state of TTN expression deficiency or mutation, affecting tumor progression." (PMID 41326912, 2025). "Through prior bioinformatics analysis, we have found a substantial relationship between TTN mutation and tumour immune cell infiltration." (PMID 39748197, 2025). "Using whole-exome (WES) and matched RNA sequencing from TNBC patient samples combined with clinical data, we analyze the genomic and transcriptomic profiles linked to TTN mutations and their impact on the tumor microenvironment." (PMID 41326912, 2025). "While chemotherapy effectively targets tumor cells, its impact on the broader mutational landscape, including passenger mutations in large genes such as Titin (TTN), remains poorly understood." (PMID 41189511, 2025). "TTN mutations are commonly observed in solid tumors and are strongly associated with an increased tumor mutational burden as well as improved responses to immune checkpoint blockade therapy." (PMID 40364249, 2025). "TTN, although historically known for its structural role in muscle tissue, has recently emerged as a biomarker of high tumor mutational burden (TMB)." (PMID 40722723, 2025). "The importance of TTN mutation in the context of tumour immunotherapy has been underscored by previous studies." (PMID 39748197, 2025). "Subsequently, the investigation into the link between TTN mutation and tumour‐infiltrating immune cells in the READ microenvironment was conducted through the utilization of the CIBERSORT algorithm." (PMID 39748197, 2025). "This study, for the first time, identifies TTN gene mutations as potential key genes affecting radiotherapy sensitivity and anti‐tumour treatment in READ patients." (PMID 39748197, 2025). "By multiplex fluorescent IHC, we found that more MDSCs were distributed in TNBC tissues with TTN mutation, and MDSCs in TTN-Mut tumors were adjacent to tumor cells in terms of spatial localization." (PMID 41326912, 2025). "Titin (TTN) mutation is proved to act a beneficial role in lung squamous carcinoma, and is related to high immunogenicity and inflammatory tumor immune microenvironment (TIME) of LUAD." (PMID 38345559, 2024). "LUAD patients with TTN mutations have an inflammatory tumor microenvironment and high levels of activated immune cells." (PMID 38430394, 2024). "Our results demonstrated that TTN mutations have the potential to modulate the tumor microenvironment, converting it into the immunosuppressive type." (PMID 36895786, 2023). "Actually, tumor common mutated genes, like TTN, FAT4, and DNAH2, were highly altered in SMC5 mutation samples, respectively, with the alteration frequency of 100%, 88%, and 81% in COAD, and 100%, 89%, and 83% in READ." (PMID 35894836, 2023). "The observed mutations of genes involved in antitumor immune responses were mostly polyclonal, but mutations in CSMD1, MUC16 and TTN occurred as clonal alterations, suggesting again a clonal advantage for those tumor cells." (PMID 36980598, 2023). "Previous studies have demonstrated that mutation of CTNNB1 or TTN of tumor cells can affect the activation and recruitment of immune cells, thus regulating the infiltration of immune cells." (PMID 37593098, 2023). "To analyze the relationship between TTN gene mutations and immune cell invasion in the tumor microenvironment, we calculated the proportion of immune cell invasion in the tumor microenvironment using the CIBERSORT algorithm." (PMID 35766333, 2022). "The TTN gene is frequently mutated in a variety of tumor types, and frequent detection of TTN in solid tumors is related to a higher tumor mutation burden and a more favorable objective response to immune checkpoint blockade immunotherapy." (PMID 35205097, 2022).
tumor (continued). "We investigated the association between TTN expression and infiltration level of immune cells in the tumor microenvironment." (PMID 35875159, 2022). "Of note, TTN mutations are associated with a high tumor mutation load, which is consistent with our study." (PMID 36231045, 2022). "TTN was identified as the most frequently mutated gene within the pancancer cohort, and its mutation number was best correlated with tumor mutation burden (TMB)." (PMID 35766333, 2022). "In another study, TTN gene mutations were correlated with poor prognosis and predicted tumour mutation burden and immunotherapy efficacy in GC." (PMID 33724653, 2021). "Tumor driver genes (such as TTN, EGFR, and PTEN) showed high mutation rates in the high METTL7B cohort compared with the rates in the low METTL7B cohort." (PMID 34604305, 2021). "TTN encodes a giant protein (>30,000 amino acids) and is rarely recognized as a tumor-associated gene." (PMID 34568069, 2021). "Titin is a large protein consisting of 34,350 amino acids, with a correspondingly large number of mutations, 15.37 protein altering somatic mutations per tumor sample and 3.98 mutations per normal sample, on average." (PMID 32029803, 2020). "Recent studies suggest that TTN mutations are associated with poor overall survival outcomes in solid tumors while demonstrating a positive response to immune checkpoint inhibitors, underscoring the potential role of TTN in tumor immunogenicity." (PMID 40364249, 2025). "Existing studies have reported an association between TTN mutations and increased tumour mutation burden, as well as their role as enhancers of immune checkpoint blockage, thereby accelerating the constructive processes and promoting the accumulation of immunosuppression within the TME." (PMID 39855898, 2025). "If TTN mutations do indeed augment anti‐tumour immunity by altering the tumour immune environment, TTN mutations could serve as new immunotherapy targets, paving the way for novel treatments for READ." (PMID 39748197, 2025). "For example, a TTN-mutated tumor might respond more favorably to treatment if it also exhibits a particular cellular growth pattern or immune cell infiltration." (PMID 40732593, 2025). "Moreover, tumor-related gene mutations such as TTN, MUC16, and KRAS with a higher number in groups were also enriched in distinct groups." (PMID 38488909, 2024). "Meanwhile, a study analyzed somatic mutations in LUSC samples based on datasets obtained from TCGA and the International Cancer Genome Consortium (ICGC) database and found that TTN mutations were associated with tumor mutational burden (TMB) and positively correlated with LUSC prognosis." (PMID 37035196, 2023).
tumor (continued). "However, in recent years, increasing studies have demonstrated that TTN is implicated in the tumor mutation burden, chemotherapy response, immunotherapy response of solid tumors." (PMID 37593098, 2023). "TTN has a high mutation rate in several types of tumor tissue." (PMID 37035196, 2023). "Second, the roles of MUC16 and TTN mutations in the anti-tumor immune process were still unclear." (PMID 35568842, 2022). "TTN mutation could also be used to represent increased tumor mutation burden (TMB) and correlated with objective response to immune checkpoint blockade (ICB)." (PMID 34368351, 2021). "TTN encodes a giant protein (>30,000 amino acids) and is rarely recognized as a tumor-associated gene; however, recent studies have suggested that mutations in the highly mutated TTN gene are closely related with high TMB status, and the potential biological mechanisms have been elucidated." (PMID 33996539, 2021). "Although we sequentially validated the diagnostic utility of the TTN gene mutation count in CRC, our discovery analyses indicated that TTN gene mutation count may also be useful for prediction of TMB in other tumor types." (PMID 32821429, 2020). "We implanted DLL4 overexpression and knockdown PDX cell lines subcutaneously into T/B-deficient nude mice to investigate whether DLL4 affects TNBC development in TTN-deficient mice, and tumor burden was limited by DLL4 expression in PDX1/PDX2 regardless of TTN genotype." (PMID 41326912, 2025). "Moreover, the potential of TTN gene mutations to activate anti‐tumour immunity by altering the TIME may serve as a novel immunotherapeutic target, paving the way for new treatment strategies for READ." (PMID 39748197, 2025). "However, the mechanisms by which TTN gene mutations impact the response of tumour patients to radiotherapy remain unclear." (PMID 39748197, 2025). "However, TTN is controversial as it is considered a tumor-associated gene." (PMID 37035196, 2023). "Therefore, mutations in the TTN gene may affect cell cycle and contribute to tumor occurrence and progression." (PMID 37239452, 2023). "Our study revealed intrinsic mechanism by which TTN regulates the tumor immune microenvironment and provided a potential target for immunotherapy in TNBC with TTN inactivation." (PMID 41326912, 2025). "Gene expression analysis showed that TTN expression was higher in tumor tissue than in normal tissue." (PMID 40854626, 2025). "The findings indicated that TTN inactivation promotes tumor immune evasion in TNBC by activating the DLL4-NOTCH2-MCT4 signaling axis." (PMID 41326912, 2025).
tumor (continued). "The research primarily focused on examining how ANKRD1 influences the radiosensitivity of TTN mutant tumour cells." (PMID 39748197, 2025). "Multiplex IHC staining showed that DLL4 and EpCAM were co-localized in tumor cells with low expression of TTN." (PMID 41326912, 2025). "This study demonstrates that TTN inactivation promotes chemoresistance in TNBC by reshaping the tumor immune microenvironment." (PMID 41326912, 2025). "By further tracking the cell cycle advancement of IR‐labeled S‐phase HCT116 and SW837 tumour cells using BrdU labelling, we observed an increased G2/M phase arrest in TTN mutant cells at 10 and 20 h postirradiation." (PMID 39748197, 2025). "TTN mutations also inhibit ANKRD1 expression via JUN disruption and enhance CD4/CD8 T‐cell infiltration, improving anti‐tumour immunity and outcomes." (PMID 39748197, 2025). "Mutations in certain large genes, such as TTN, NEB, SYNE1, MUC16, and OBSCN, have previously been associated with tumor mutation burden (TMB)." (PMID 38473427, 2024). "Meanwhile, patients with TTN-mutant were found to have high immunogenicity and inflammatory tumor immune microenvironment (TIME)." (PMID 37038181, 2023). "TTN expression was favorably associated with the infiltration levels of effector T cells owning an inflammatory TiME and TMB in numerous tumor types, and therefore is linked with susceptibility to immune checkpoint inhibitors." (PMID 37033966, 2023).
tumor (continued). "Another natural antisense transcript, the lncRNA TTN-AS1, regulates in cis the activity of the Titin gene promoter and stimulates melanoma cell migration, invasion, and tumor formation in vivo." (PMID 35159386, 2022). "The results manifested that tumor tissues had a significantly decreased TTN expression compared with that in normal tissues in LUAD." (PMID 35875159, 2022). "Other researchers also observed that TTN, OBSCN, and ADAMTS12 genes were frequently mutated in cfDNA WES although tumor types are different as HCC." (PMID 35402275, 2022). "In low-WM score group, the top genes with the highest mutation frequency were KRAS (26%), TTN (26%), and MUC16 (24%), showing that the high-WM score group had more tumor mutation burden than the low-WM score group." (PMID 35154267, 2022). "Another important result in our study was the correlation between TTN expression and tumor-infiltrating lymphocytes." (PMID 35875159, 2022). "Since TTN expression was significantly changed in various tumor tissues, especially in LUAD, we investigated the Prognostic value of TTN expression in LUAD patients." (PMID 35875159, 2022). "Both Oncomine and TIMER databases showed consistent differences between tumor and normal tissues, which means TTN was a differentially expressed gene and deserved further study." (PMID 35875159, 2022). "On the basis of our findings and rigorous validation, we found TTN was strongly correlated with prognosis and tumor-infiltrating lymphocytes." (PMID 35875159, 2022). "Specially, as the previous studies reported, TTN out of the top 20 genes is rarely considered a tumor-related gene." (PMID 34900664, 2021). "Collectively, these findings indicated that TTN/OBSCN ‘Double‐Hit’ suggested ‘immune‐hot’ tumours, which has potential implications for optimizing immunotherapy." (PMID 33624434, 2021). "CLEC5A expression was significantly associated with TTN and CDK12 mutations and affected the copy number of tumor progression and immune-related genes." (PMID 34712666, 2021). "TTN-TMB was significantly correlated with TMB-WES across all 33 tumor types, with the exception of PCPG, TGCT, THYM, MESO, DLBC, and CHOL (FWER, raw p-value*33, <0.05)." (PMID 32821429, 2020).